RN7SL508P (RNA, 7SL, cytoplasmic 508, pseudogene)
Gene: Miscellaneous RNA gene on chromosome 12 (118,993,857 to 118,994,159, forward strand). Ensembl gene ENSG00000244112.
Homologues: Orthologues: chimpanzee Metazoa_SRP (97% identical), macaque Metazoa_SRP (94% identical). Paralogues in human: RN7SL1 (83% identical), RN7SL2 (83% identical), RN7SL3 (82% identical), RN7SL230P (80% identical), RN7SL126P (79% identical), RN7SL45P (79% identical), RN7SL575P (79% identical), RN7SL147P (78% identical), RN7SL665P (78% identical), RN7SL7P (78% identical), RN7SL296P (78% identical), RN7SL503P (78% identical), and 703 more.